BRAF (B-Raf proto-oncogene, serine/threonine kinase)
Diseases named in the same sentence as BRAF in open-access papers (continued):
Sharing a sentence is not in itself a finding about the gene and the disease.
melanoma (continued). "Moving forward in melanoma, adding a feedback inhibitor, such as SHP2, may improve outcomes in BRAF V600E-mutant patients, as may the combination of a RAF dimer inhibitor plus MEK inhibitor in RAS Q61X-mutant melanoma." (PMID 36058945, 2022). "When the expression of lncRNA-TINCR is decreased in metastatic melanoma, its downregulation promotes the expression level of proliferation-, migration- and invasion-related marker genes and increases its resistance to drugs such as BRAF and MEK inhibitors in melanoma progression." (PMID 36601121, 2022). "Nonetheless, 90 days of exposure of melanoma cells to BRAF inhibitors displays no multidrug resistance, leading to the elimination of IDTC markers such as NGFR and KDM5B and permanent resistance." (PMID 36224606, 2022). "BRAF inhibitors (vemurafenib, dabrafenib, encorafenib) and MEK inhibitors (trametinib, binimetinib, cobimetinib) are used in molecularly targeted treatment of melanoma." (PMID 35406444, 2022). "Resistance to BRAF inhibitors is related to reduced cAMP levels in BRAF wild-type and NRAS wild-type melanoma cells and restoring cAMP levels using forskolin (FSK), a cAMP activator, while IBMX, a universal inhibitor of PDEs, sensitizes melanoma cells to BRAF inhibitors." (PMID 35805104, 2022). "However, not all patients responded, with the combination tending to show most benefit in patients with BRAF-mutant disease, elevated LDH or M1c stage melanoma." (PMID 35538491, 2022). "In our dataset, melanomas with FER amplification had frequent NF1 inactivation but lacked BRAF and NRAS alterations." (PMID 35706047, 2022). "Trametinib and VX11E, but not SHP099, had substantial activity across melanoma cell lines enriched in the BRAF mutant as well as some mild activity in KRAS mutant tumors such as pancreas." (PMID 35905710, 2022). "Logistic regression depending on BRAF status was not significant for distant metastasis and death from melanoma, denoting that, in our study, BRAF status alone did not predict the risk of adverse events." (PMID 35326682, 2022). "Loss of NF1 has been reported to confer resistance to BRAF inhibitors and to some irreversible (but not allosteric) MEK inhibitors in melanoma cell lines." (PMID 36358725, 2022). "In addition, Src mediated the reactivation of RTK signaling responsible for the induced resistance of BRAF and MEK inhibitors during the treatment of BRAF mutant melanoma." (PMID 35625759, 2022). "There have been no clinical trials directly comparing the effectiveness of immunotherapy versus BRAF inhibitor and MEK inhibitor in BRAF-mutant advanced melanoma; therefore, the best sequence of therapy in this patient group remains unknown." (PMID 35492830, 2022). "In 2019, Li and colleagues demonstrated that BRAFV600E-TFEB-ZKSCAN3-autophagy and lysosome biogenesis axis are involved in tumor resistance to targeted therapy in BRAF mutant melanomas, leading to the aberrant expression of TGF-beta pathway and impairing the tumor response to BRAF inhibition." (PMID 35008395, 2022). "In fact, matching-adjusted indirect comparisons of dual immune checkpoint blockade with ipilimumab and nivolumab versus combined BRAF and MEK inhibition in patients with melanoma show that tentative benefits from immunotherapy emerge after the first 12 months of treatment." (PMID 36522538, 2022). "In BRAF inhibitor-resistant melanoma cells, expression of the serine biosynthetic enzymes PHGDH, PSAT1, and PSPH is enhanced to support folate cycle metabolism, and depletion of PHGDH sensitizes resistant cells to BRAF inhibitors." (PMID 35011702, 2022). "Melanomas with NF1 mutation typically occur on chronically sun-exposed skin or in older individuals, show a high mutation burden, and do not express BRAF or NRAS mutations." (PMID 36232957, 2022).
melanoma (continued). "The combination of BRAF and MEK inhibitor has been demonstrated to be more effective than a single agent BRAF inhibitor even though no direct studies have been conducted to identify which combination would be more adequate for V600K melanoma patients." (PMID 35160279, 2022). "ACA-28 and its lead derivative ACAGT-007a (GT-7; described as 2b in the previous reports) selectively induce apoptosis in several ERK-active melanoma cell lines, including SK-MEL-28, expressing the oncogenic mutant BRAF (V600E), by further stimulating ERK phosphorylation levels." (PMID 35203351, 2022). "Enhancement of BRAF and MEK inhibitors can influence melanoma cells’ signaling and activate CAFs." (PMID 35558554, 2022). "Mutant BRAF, and downstream kinase protein MEK, have proved viable targets for melanoma therapies." (PMID 36212431, 2022). "BRAF and MEK inhibitors are currently used as a combined targeted therapy for melanoma patients to reduce possible therapeutic failure due to the activation of other pathways, including PIK3–Akt, or to the onset of other mutations occurring in the MAPK pathway." (PMID 35335966, 2022). "Here we employed pre-clinical melanoma models with high levels of AXL and investigated the anti-cancer effects and molecular mechanisms induced by the AXL inhibitor BGB324, when used alone and in combination with the BRAF inhibitor vemurafenib." (PMID 35332208, 2022). "BRAF and MEK inhibitors have shown clinical benefit in patients with BRAF-mutant melanoma." (PMID 35327519, 2022). "The evaluation was based on 37 patients (19 f, 62 ± 13 y/o) with unresectable metastasized melanomas who underwent whole-body 18F-FDG PET/MRI and PET/CT scans on the same day before the initiation of therapy with checkpoint inhibitors and/or BRAF/MEK inhibitors." (PMID 36140504, 2022). "BRAF and MEK inhibitors have revolutionized treatment for patients with melanoma." (PMID 35492830, 2022). "Indolium 1 is well-tolerated in mice and, given its efficacy against vemurafenib-resistant melanoma, works through a mechanism that is independent of BRAF." (PMID 35624662, 2022). "The main indication for BRAF and MEK inhibitors is BRAF V600 mutant melanomas." (PMID 36254250, 2022). "Clinical guidelines strongly recommend testing BRAF, NRAS and KIT in all melanomas." (PMID 35159047, 2022). "SOX10 immunofluorescence analysis in A375 (BRAF V600E), MeWo (wild-type for BRAF and NRAS), and 1205Lu (BRAF V600E) melanoma cell lines showed a similar level of heterogeneity and confirmed the co-presence of SOX10-low and -high expressing cells in basal culture conditions." (PMID 35296667, 2022). "Target therapies are effective just with exon 15/codon 600 BRAF- mutant melanoma, adopting BRAF inhibitors in combination or not with MEK inhibitors." (PMID 36012593, 2022). "The reduction in cellular proliferation when targeting EEF2K was similar to that observed when the BRAF (positive control) was knocked down, suggesting that EEF2K might be an important target in melanoma." (PMID 35408842, 2022). "Collectively, these data demonstrate that Activin-A inhibits antitumor CTLs in both BRAF wild-type and mutant melanoma models, and without increasing the frequency of Tregs." (PMID 35580932, 2022). "In addition, the expression level of lncRNA-TSLNC8 is downregulated in BRAF inhibitor-resistant melanoma cells, and its low expression attenuates the toxicity response of tumor cells to PLX4720 (a type of BRAF inhibitor)." (PMID 36601121, 2022). "Moreover, we further highlighted the role of targeting BRAF, NRAS and MC1R in melanoma prevention and treatment." (PMID 36551302, 2022).
melanoma (continued). "In one study, KDs accelerated tumor growth in a BRAF mutant melanoma mouse model, whereas the growth of NRAS mutant and BRAF wild-type melanomas remained unaffected, suggesting that the tumor genetic background might determine KD responsiveness." (PMID 35851093, 2022). "While combined anti-BRAF/MEK therapy is initially highly effective in patients with melanomas harboring mutant BRAF, eventual resistance is not uncommon." (PMID 35326683, 2022). "Accordingly, BRAF inhibitors vemurafenib, dabrafenib, and encorafenib, as well as mitogen-activated protein kinase kinase (MEK) inhibitor trametinib, cobimetinib, and binimetinib, are applied to the targeted treatment of melanoma." (PMID 36003368, 2022). "This opened a new avenue for specific therapies targeting BRAF-negative melanomas that account for a significant amount of all human melanomas and lack effective treatments." (PMID 35426591, 2022). "In our previous publication, we have shown that both BRAF- and NRAS-mutant melanoma cell lines significantly upregulated ERK5 signaling when subjected to MEKi using trametinib, selumetinib, binimetinib or cobimatinib, or ERK1/2 inhibition (ERKi) using GDC-0994." (PMID 34299213, 2021). "Patients with advanced melanoma were recruited in CheckMate 067 regardless of the tumor’s BRAF status; hence, nivolumab plus ipilimumab combination therapy and nivolumab monotherapy were approved for both BRAF-positive and BRAF-negative melanomas." (PMID 34914610, 2021). "To examine the role of PTEN in resistance to BRAF inhibition, we created BRAFi-resistant melanoma models with/without wild-type PTEN." (PMID 34282258, 2021). "For example, BRAF-mutated melanoma, NSCLC, and hairy cell leukemia satisfactorily responded to vandetanib, a drug that targets the BRAF V600E mutation, while BRAF-mutated CRC does not." (PMID 33785068, 2021). "A possible reason for the distinct metabolite profiles between the BRAF mutant melanoma xenografts could be that A375 and WM47 cells originate from primary and metastatic melanomas, respectively." (PMID 33498757, 2021). "In line with prognosis, genetic alterations occurring in mucosal melanoma are different than those of cutaneous wild-type melanoma (BRAF, NRAS and NF1 negative)." (PMID 34571863, 2021). "In other malignancies such as melanoma, BRAF positivity does not factor into treatment options for node negative disease and has no known prognostic significance, but it informs management in the metastatic setting." (PMID 33659040, 2021). "In melanoma and TC, unidentified importin and CRM1 shuttle RAF proteins (particularly BRAF) into and out of the nucleus, which phosphorylate MAPK/ERK kinases (MEKs) within the mitogen-activated protein kinase (MAPK) cascade upon activation by proto-oncogenes Rat sarcoma (RAS) proteins." (PMID 33578751, 2021). "Consequently, combination therapies using BRAF and MEK inhibitors such as cobimetinib and trametinib are becoming the standard of melanoma treatment." (PMID 34441278, 2021). "Overall our findings indicate the BRAF-MEK-CDK4/6i can be employed in combination with ACT and provides additional evidence that supports clinical studies of CDK4/6i in combination with BRAF-MEKi in advanced melanoma." (PMID 34944961, 2021). "BRAF inhibitor monotherapy (BRAFi) with the approval of vemurafenib and dabrafenib by the US Food and Drug Administration (FDA) constituted pivotal treatments against melanoma." (PMID 33672955, 2021). "Although they are not a form of immunotherapy, the development of BRAF inhibitors of the MAP kinase pathway was also groundbreaking for the treatment of advanced melanoma." (PMID 34885172, 2021). "Targeting the BRAF V600E oncogene with a single BRAF inhibitor shows response rates of approximately 50% in melanomas or non-small cell lung cancers, but no activity in colorectal cancers, anaplastic thyroid cancers, or several other types of cancers." (PMID 33907275, 2021).
melanoma (continued). "The therapeutic success of BRAF inhibitors (BRAFi) and MEK inhibitors (MEKi) in BRAF-mutant melanoma is limited by the emergence of drug resistance, and several lines of evidence suggest that changes in the tumor microenvironment can play a pivotal role in acquired resistance." (PMID 33467521, 2021). "Due to the high response rate, rapid response kinetics, and favorable drug safety profile in metastatic and adjuvant settings, targeted therapy with BRAF and MEK inhibitors may also provide an effective neoadjuvant treatment in melanoma patients." (PMID 35008274, 2021). "Targeted therapies (BRAF and MEK-inhibitors) and immune checkpoint inhibitors (ipilimumab, nivolumab, pembrolizumab) have provided significant survival benefits for patients with stage III–IV melanoma." (PMID 34745967, 2021). "For example, BRAF-mutated melanomas, which do not express significant amounts of the EGFR receptor, can be managed by a combination of BRAF and MEK inhibitors." (PMID 34681592, 2021). "Interestingly, the vorinostat effect was BRAF (V600E) mutant and MAPK inhibitors-resistant melanoma specific." (PMID 34725562, 2021). "Interestingly, a negative association between MC1R variants and BRAF mutations has been described for head/neck melanomas, suggesting a difference in the pathogenesis of melanomas located at different skin sites, head/neck or trunk, which could contribute to their divergent prognoses." (PMID 34356109, 2021). "Retrospectively, three MCPyV and BRAF-positive melanoma samples were analyzed using NGS (the fourth sample was not enough for NGS)." (PMID 33535453, 2021). "To understand the molecular mechanism of PTEN in resistance to BRAF inhibition, we previously created BRAFi-resistant melanoma models with/without wild-type PTEN." (PMID 34282258, 2021). "The number of CD40+SOX10+ melanoma cells increased to 103 post BRAF treatment in the one tumor that did not have CD40+SOX10+ cells prior to BRAF inhibitor treatment." (PMID 34092233, 2021). "Thus, more detailed experiments using combinations of BRAF inhibitors and PITX1 inducing drugs for melanoma treatment will lead to the development of anticancer agents through novel targets." (PMID 34526609, 2021). "For OS, a KPS ≥ 80%, a positive BRAF mutation status, a small PTV, the absence of extracranial metastases, as well as a GPA and melanoma molGPA > 2 were prognostic factors." (PMID 33993415, 2021). "This review summarizes prospectively and retrospectively generated clinical evidence on modern melanoma therapy, focusing on immunotherapy and targeted therapy with BRAF kinase inhibitors and MEK kinase inhibitors (BRAF/MEK inhibitors), including recent data presented at major conference meetings." (PMID 33804800, 2021). "In patients with rapidly progressive melanoma, cerebral metastases and/or elevated level of lactate dehydrogenase (LDH), combination therapy with nivolumab-ipilimumab is usually preferred, in particular in patients with BRAF-wild type melanoma." (PMID 33765967, 2021). "The average study participant was male, older than 60 years, diagnosed with stage IV melanoma BRAF wild type (73% of patients), and had received no previous systemic treatments prior to the study." (PMID 33449393, 2021). "GAB2 CNV gains have also been reported in non-sun-damaged melanoma, including AMs and MUs, and have been reported to be mutually exclusive of BRAF, NRAS, and KIT aberrations." (PMID 33826614, 2021). "Although further studies between BRAF and VISTA need to be done, especially in the setting of melanoma, where VISTA expression could influence the efficacy of BRAF inhibitor therapy." (PMID 34465822, 2021). "We observed that gynecologic melanoma harbored distinct mutation rates in c-KIT, BRAF, SF3B1, KRAS and NRAS genes compared with non-gynecologic melanoma." (PMID 34102999, 2021). "Following BRAF or MEK inhibitor treatment, melanoma tumors had acquired EGFR expression." (PMID 34360915, 2021).
melanoma (continued). "Collectively, although CDK4/6 inhibition has no substantial effect on the metabolic phenotype following BRAF/MEK targeted therapy in melanoma, CDK4/6 inhibition alone significantly enhances mitochondrial metabolism." (PMID 33572972, 2021). "Though NF1 mutations often occur in melanomas without BRAF or NRAS mutations, approximately 4% of the BRAF and NRAS mutated melanomas also harbor NF1 mutations." (PMID 35008286, 2021). "We also show that BRAF-MEKi but not CDK4/6i enhanced MHC Class I expression in melanoma cell lines in vitro." (PMID 34944961, 2021). "The study was designed as an observational retrospective chart review study, which included 382 patients with advanced BRAF V600 mutant melanoma, who received TT in a real-world setting and were not involved in clinical trials." (PMID 34064013, 2021). "The respective BRAF resistant cell lines (A375R, WM9R, WM35R and WM902BR, as well as BRAF wildtype melanoma cell lines (MV3, SK-Mel30) and normal human epidermal melanocytes (NHEM) showed no significant change in miR-129-5p expression after Vemurafenib treatment." (PMID 34063443, 2021). "Our analyses have revealed that inhibition of CDK4/6 upregulates glutamine and fatty acid-oxidation-dependent mitochondrial metabolism in BRAF mutant melanoma cells, but they do not alter glycolysis nor the metabolic response to MAPK inhibitors." (PMID 33572972, 2021). "Interestingly, knock-down of PERK in both resistant melanoma cell lines with impaired PTEN enhanced the sensitivity to BRAF inhibitor, indicating that PERK is involved in regulating resistance to BRAF inhibition in PTEN impaired melanoma." (PMID 34282258, 2021). "None of the cases were found to harbor BRAF, NF1 and PDGFRA mutations in melanomas of the female genital tract." (PMID 34102999, 2021). "Inhibition of BRAF/MEK signaling by silencer (si)RNA and pharmacological inhibition decreased the production of pro-tumorigenic factors such as IL-1α/β, IL-6, IL-8, IL-10, and VEGF by melanoma cells." (PMID 34576054, 2021). "Recent approval and early phase trials with immune checkpoint inhibitors, such as ipilimumab and nivolumab, BRAF inhibitors (e.g. Dabrafanib) and MEK inhibitors (e.g. Binimetinib) has begun for adolescents with advanced malignant melanoma at selected pediatric centers." (PMID 33996584, 2021). "BRAF is a component of the MAPK signaling pathway; it could activate the downstream MEK1 and MEK2 and further lead to the proliferation and metastasis of melanoma." (PMID 34582363, 2021). "Interestingly, melanoma actively releases eNAMPT (extracellular NAMPT), and cells resistant to BRAF inhibitors have higher eNAMPT levels." (PMID 34068679, 2021). "Melanoma is known as a “cold” tumor due to the poor responses to ICI therapy; the combination of B‐Raf Proto‐Oncogene, serine/threonine kinase (BRAF) and Methyl Ethyl Ketone (MEK) inhibitors (BRAFi + MEKi) is an FDA‐approved approach to therapy BRAF V600E/K‐mutant melanoma." (PMID 34459122, 2021). "A panel of BRAF inhibitors (BRAFi-s) (vemurafenib, dabrafenib, encorafenib, etc.)and a series of MEK inhibitors (MEKi-s) (cobimetinib, trametinib, binimetinib, etc.)have revolutionized the treatment of melanoma patients." (PMID 34885166, 2021). "Together, these data suggest that CDK4/6 activity does not alter glycolysis in BRAF mutant melanoma cells, nor does it effect the glycolytic response following MAPK pathway inhibition." (PMID 33572972, 2021). "Furthermore, we performed XAF1 knockdown in additional BRAF and NRAS mutant melanoma cultures (Figure [Link], [Link]) and observed the same trend." (PMID 33734579, 2021). "The NF1-mutant category refers to cases lacking either BRAF or RAS mutations, whereas NF1 mutations can also arise as a mechanism of resistance to RAF/MEK-targeted therapies in BRAF-mutated melanoma." (PMID 34331013, 2021). "Therefore, we generated tumor xenografts in mice using BRAF mutant A375 and WM47, NRAS mutant WM3000, and triple-wildtype WM3311 human melanoma cells." (PMID 33498757, 2021).